KCNQ1OT1 (KCNQ1 opposite strand/antisense transcript 1)
Diseases named in the same sentence as KCNQ1OT1 in open-access papers (continued):
Sharing a sentence is not in itself a finding about the gene and the disease.
osteosarcoma (continued). "Besides that, KCNQ1OT1 was shown to regulate the osteosarcoma cell behaviors and its response to cisplatin via regulating Kcnq1/DNA methyltransferase 1 mediated KCNQ1 expression." (PMID 31909901, 2020). "The result revealed that KCNQ1OT1 was highly expressed in osteosarcoma tissues and cells." (PMID 32953888, 2020). "Similarly, our study found that the expression of KCNQ1OT1 in osteosarcoma was also upregulated which is consistent with previous studies." (PMID 32953888, 2020). "It reported that the expression of KCNQ1OT1 in osteosarcoma tissues was significantly increased than adjacent tissues, and the high expression of KCNQ1OT1 may promote the development of osteosarcoma." (PMID 32953888, 2020). "Therefore, the knockdown of KCNQ1OT1 inhibits the occurrence and development of osteosarcoma via regulating the miR-129-5p/LARP1 axis." (PMID 32953888, 2020). "Additionally, KCNQ1OT1 exerted tumor-promoting roles in colorectal carcinogenesis, non-small-cell lung carcinoma, hepatocellular carcinoma, bladder cancer, glioma, osteosarcoma, gastric cancer and OC." (PMID 36100884, 2022). "However, the expression and role of KCNQ1OT1 in osteosarcoma need to be further elucidated." (PMID 32953888, 2020). "The lncRNA KCNQ1OT1 competitively binds to miR-34c-5p to indirectly upregulate ALDOA and facilitates aerobic glycolysis, promoting osteosarcoma proliferation." (PMID 35927226, 2022). "Many lncRNAs, such as lncRNA OR3A4, lncRNA KCNQ1OT1, and LINC00514, have been demonstrated to be involved in osteosarcoma progression, drug resistance, and prognosis." (PMID 34316513, 2021). "LncRNA KCNQ1OT1 functions as a competing endogenous RNA (ceRNA) for miR-4458, regulating the expression of CCND2 and enhancing the progression of osteosarcoma." (PMID 34015762, 2021). "Collectively, it suggests that downregulation of KCNQ1OT1 inhibits proliferation, invasion, and drug resistance by regulating miR-129-5p-mediated LARP1 in osteosarcoma cells." (PMID 32953888, 2020). "Moreover, KCNQ1OT1 promoted OS cell proliferation, migration, invasion, and EMT in primary osteosarcoma cells by activating β-catenin." (PMID 34827600, 2021). "KCNQ1OT1 expression is also upregulated in osteosarcoma and non-small cell lung cancer tissues, and its high expression indicates the adverse prognosis of patients with these diseases." (PMID 33909822, 2021). "Therefore, the downregulation of KCNQ1OT1 inhibited proliferation, invasion, and drug resistance by regulating miR-129-5p-mediated LARP1 in osteosarcoma." (PMID 32953888, 2020). "In summary, our current study reveals that the knockdown of KCNQ1OT1 inhibits the occurrence and development of osteosarcoma by regulating the miR-129-5p/LARP1 axis, which suggests that KCNQ1OT1 might be a new biomarker related to proliferation and drug resistance of osteosarcoma." (PMID 32953888, 2020).
colon cancer (21 papers, 2015 to 2025). "In this study, we aimed to study the combined effect of allele variation of KCNQ1OT1 polymorphism rs35622507 and methylation status of KCNQ1OT1 promoter in the treatment of colon cancer." (PMID 35193115, 2022). "In our research, we discovered that levels of KCNQ1OT1 expression were associated with the prognosis of colon cancer patients." (PMID 35193115, 2022). "In this study, we examined the combined outcome of allele variation of the KCNQ1OT1 polymorphism rs35622507 and methylation status of KCNQ1OT1 promoter on the drug resistance in the treatment of colon cancer and its underlying molecular mechanisms." (PMID 35193115, 2022). "The upstream lncRNA KCNQ1OT1 was also detected and is considered a potential diagnostic biomarker for colon and rectal cancer and enhanced drug resistance in colon cancer cells." (PMID 35116071, 2022). "High KCNQ1OT1 expression is associated with poor overall survival in colon cancer patients." (PMID 38361755, 2024). "KCNQ1OT1, has also prove that induce protective autophagy and chemoresistance and its high expression is associated with poor OS of colon cancer patients, suggesting that patients with overexpression of KCNQ1OT1 might be resistant to chemotherapy treatments." (PMID 31632922, 2019). "With the development of bioinformatics, RNA sequencing (RNA-Seq) can be used to analyze global transcript data to investigate KCNQ1OT1 mediated oncogenicity in colon cancer cells." (PMID 38361755, 2024). "The role of lncRNA KCNQ1 opposite strand/antisense transcript 1 (KCNQ1OT1) in colon cancer involves various tumorigenic processes and has been studied widely." (PMID 38361755, 2024). "In the current study, we utilized retroviral vector pSEB61 to establish a stable HCT116-siKCN cell line to explore the downstream genes of KCNQ1OT1 and their contribution to the colon cancer phenotype." (PMID 38361755, 2024). "With the most regulated connections in the network, the effect of KCNQ1OT1 on lncRNAs in the development of colon cancer has been confirmed in several studies." (PMID 39795006, 2024). "KCNQ1OT1 is overexpressed in many human tumors, including liver cancer, colon cancer, acute myeloid leukemia, and lung cancer." (PMID 35432529, 2022). "Actually, the result of the interaction between lncRNA KCNQ1OT1 and miR-34a in colon cancer also showed the transfection of miR-34a reduced luciferase activity of wild-type KCNQ1OT1, but not the mutant one." (PMID 35193115, 2022). "LncRNA KCNQ1OT1 has been reported to promote the chemoresistance of colon cancer by inhibiting the expression of downstream miRNA miR-34a." (PMID 35193115, 2022). "The effect of KCNQ1OT1 on lncRNAs in the development of colon cancer has been confirmed in several studies." (PMID 36127676, 2022). "Among the predicted lncRNA/circRNA, KCNQ1OT1 was involved in the regulation of tumor microenvironment in colon cancer by regulating CD155 expression." (PMID 36313331, 2022). "In colon cancer cells, KCNQ1OT1 is mainly distributed in the cytoplasm, which is consistent with the findings of our study." (PMID 32564010, 2020). "In colon cancer, KCNQ1OT1 was also identified to be elevated expression and correlated with poor overall survival of cancer patients." (PMID 31909901, 2020). "Previous studies investigating the effects of silencing lncRNA KCNQ1OT1 in colon cancer cells relied primarily on transient transfection with small interfering RNAs (siRNAs) using Lipofectamine, which may have variable and transient effects." (PMID 38361755, 2024). "Therefore, investigating the adjacent genes regulated by lncRNA KCNQ1OT1 is necessary to determine targeted treatments for colon cancer." (PMID 38361755, 2024). "However, further studies are required to investigate the therapeutic effects of using vectors with silencing KCNQ1OT1 in the colon cancer model." (PMID 38361755, 2024).
colon cancer (continued). "Our findings indicate that lncRNA KCNQ1OT1 plays a critical role in colon cancer development and targeting it may provide a promising option for clinical therapy." (PMID 38361755, 2024). "Thus, this study aimed to explore the molecular mechanisms through which KCNQ1OT1 is involved in colon cancer tumorigenesis by performing a global bioinformatics analysis of downstream genes." (PMID 38361755, 2024). "Our study suggests that lncRNA KCNQ1OT1 may provide a promising therapeutic strategy for colon cancer." (PMID 38361755, 2024). "In addition, a study showed that lncRNA KCNQ1 opposite strand/antisense transcript 1 (KCNQ1OT1) enhances autophagy in colon cancer." (PMID 36899946, 2023). "Due to these multifaceted roles, KCNQ1OT1 could be a promising target for colon cancer therapeutics." (PMID 36899946, 2023). "Even exosome-derived KCNQ1OT1 could mediate immune escape by regulating PD-L1 ubiquitination in colon cancer." (PMID 36313331, 2022). "Subsequently, we show for the first time that miR-34a is a target of KCNQ1OT1, whereas KCNQ1OT1 might partially make colon cancer cells more vulnerable to L-OHP treatment by inhibiting protective autophagy and boosting apoptosis." (PMID 35193115, 2022). "Although SNHG1 or KCNQ1OT1 has been reported to be significantly correlated with the prognosis of colon cancer, the regulatory mechanism of SNHG1 or KCNQ1OT1 underlying the pathogenic differences between colon cancer and rectal cancer has not been well explored." (PMID 33194594, 2020). "Thus, we confirmed KCNQ1OT1’s role in influencing colon cancer." (PMID 38361755, 2024). "KCNQ1OT1 could be a promising target for the treatment of colon cancer." (PMID 38361755, 2024). "Interestingly, tumor xenografts were almost non-existent at day 30 after implantation suggesting that silencing KCNQ1OT1 using pSEB61 retroviral vector may be a promising option for colon cancer therapy." (PMID 38361755, 2024). "However, the role of KCNQ1OT1 in colon cancer remains incomplete." (PMID 38361755, 2024). "Therefore, it is reasonable to speculate that KCNQ1OT1-mirNAs-SQSTM1 play an important role in the activation of pyroptosis in colon cancer." (PMID 36127676, 2022). "KCNQ1OT1 mediates methotrexate resistance in HT29 and Caco2 colon cancer cell lines and promotes oncogenic properties in SW480 and DLD1 colon cancer cell lines." (PMID 38361755, 2024). "Survival analysis showed that higher expression of AC131571.1, ANO1‐AS2, ITCH‐IT1, ARHGEF26‐AS1, AP004609.1, LINC00491, KCNQ1OT1, MACROD2‐IT1, TSSC1‐IT1 or LINC00355 was correlated to poor OS in patients with colon cancer." (PMID 31965704, 2020). "In conclusion, our study indicates that silencing KCNQ1OT1 in HCT116 and SW480 cells may suppress colon cancer progression by negatively regulating DNA replication and the mitotic cell cycle phase-related pathways, targeting the downstream PCNA and CCNE2." (PMID 38361755, 2024). "LncRNA KCNQ1OT1, a well-established lncRNA acts as an oncogene, was found to be highly expressed in many malignant tumors, such as non-small-cell lung carcinoma (NSCLC), colon cancer, colorectal cancer, and so on." (PMID 33345272, 2021). "As lncRNAs KCNQ1OT1 and SNHG1 exhibited high potential in diagnosing patients with colon cancer or rectal cancer, we further validated their experimental gene expression pattern and diagnostic performance via published GEO datasets including GSE21510, GSE23878, and GSE9348." (PMID 33194594, 2020). "Consistent with previously reported, in our study, we identified that the lncRNA KCNQ1OT1 was up-regulated in 341 colon cancers compared with 27 non-tumor samples." (PMID 29420609, 2018). "Therefore, we think KCNQ1OT1 and WT1-AS may play a more significant role in the pathogenesis and prognosis of colon cancer." (PMID 29420609, 2018).
myocardial infarction (19 papers, 2017 to 2025). Gross necrosis of the myocardium, as a result of interruption of the blood supply to the area, as in coronary thrombosis. "LncRNA KCNQ1OT1, an antisense non-coding RNA implicated in cardiac development, has been observed to increase in myocardial infarction patients." (PMID 41169895, 2025). "Early evidence has demonstrated that KCNQ1OT1 is associated with risk factors for ischemic stroke, for example, diabetes and myocardial infarction." (PMID 30945454, 2019). "Previous research has shown that knockdown of KCNQ1OT1 can modulate adiponectin receptor 1 and attenuate ischemia-reperfusion (I/R) injury after acute myocardial infarction (AMI) by affecting the p38 MAPK/NF-κB signaling pathways." (PMID 38414735, 2024). "Mounting evidence manifested that lncRNA KCNQ1OT1 participated in regulating cell progression and differentiation among various diseases such as cancer, fracture, and myocardial infarction." (PMID 36278219, 2022). "Evidence demonstrated that KCNQ1OT1 activated inflammatory response and promoted apoptosis of microvascular endothelial cells in acute myocardial infarction." (PMID 36278219, 2022). "For instance, down-regulation of KCNQ1OT1 facilitates cell viability while repressing cell apoptosis and production of inflammatory cytokines in myocardial infarction." (PMID 34301223, 2021). "A reduced KCNQ1OT1 expression can provide protection against heart injury in the course of I/R after myocardial infarction, and KCNQ1OT1 can modulate the expression of genes through a network of lncRNA/miRNA/mRNA interactions." (PMID 35053194, 2021). "Downregulation of lncRNA KCNQ1OT1 protects against MI/RI following acute myocardial infarction." (PMID 38172743, 2024). "KCNQ1OT1 could competitively bind with miR-466 to mediate downstream Tead1 expression, promoting apoptosis of cardiomyocytes during acute myocardial infarction." (PMID 36278219, 2022). "Oxidative stress following myocardial infarction could be accelerated via the KCNQ1OT1/miR-130a-3p/ZNF791 axis." (PMID 36278219, 2022). "As previously reported, KCNQ1OT1 could aggravate inflammatory response in myocardial infarction via the Notch pathway." (PMID 36278219, 2022). "KCNQ1 overlapping transcript 1 (KCNQ1OT1) was found to be increased in the serum of myocardial infarction (MI) patients, ischemia/reperfusion (I/R) mouse and hypoxia/reoxygenation (H/R)-induced cell model." (PMID 34421622, 2021). "In cardiac, Kcnq1ot1 recruits DNA methyltransferase 1 (DNMT1) to the RUNX3 promoter region and inhibit Runx3 expression, regulating the proliferation and apoptosis of CMEC and induces inflammatory response during myocardial infarction." (PMID 34604208, 2021). "One of the genes included in the KCNQ1OT1 imprinted cluster, cyclin-dependent kinase inhibitor 1C (CDKN1C), was postulated as a novel female-specific biomarker of left ventricular dysfunction after myocardial infarction." (PMID 32664454, 2020). "In one study enrolling 414 patients with acute myocardial infarction (AMI) treated by primary percutaneous coronary intervention, levels of hypoxia inducible factor 1A antisense RNA 2, KCNQ1OT1, MALAT1 and ANRIL in peripheral blood cells were significantly altered with AMI." (PMID 32241300, 2020).
glioma (18 papers, 2018 to 2024). A benign or malignant brain and spinal cord tumor that arises from glial cells (astrocytes, oligodendrocytes, ependymal cells). "The results indicated that KCNQ1OT1 was upregulated in glioma tissues compared with adjacent tissues, which was associated with poor prognosis." (PMID 35935338, 2022). "Of these, CCNE2 and PCNA have been identified as key targets of KCNQ1OT1 regulators for promoting cell proliferation in breast cancer and glioma." (PMID 38361755, 2024). "For example, KCNQ1OT1, a miR-504 sponge that targets cyclin-dependent kinase 16 in liver cancer and cyclin E2, a miR-370 sponge in glioma act as ceRNA by neutralizing miR-9." (PMID 38875399, 2024). "Another study shown that lncRNA KCNQ1OT1 promotes proliferation and invasion of glioma cells by targeting the miR-375/YAP pathway." (PMID 35935338, 2022). "In glioma, KCNQ1OT1 was upregulated and KCNQ1OT1 upregulation promotes tumor cell proliferation through activating miR-370/CCNE2 axis." (PMID 34404765, 2021). "Knockdown of KCNQ1OT1 inhibited cell proliferation, migration and invasion, and promoted apoptosis in U87 and U251 glioma cells." (PMID 34827600, 2021). "KCNQ1OT1 is an lncRNA highly expressed in a variety of malignant tumors, such as colorectal, lung, tongue, and liver cancers, adrenal cortical tumors, and glioma." (PMID 32953888, 2020). "KCNQ1OT1 promoted glioma cell progression via decreasing miR-370 expression and miR-370 inversely modulated KCNQ1OT1 expression." (PMID 29467441, 2018). "The results of this study suggest KCNQ1OT1 might contribute to glioma malignancy, and targeting the KCNQ1OT1/miR370/CCNE2 axis may be a promising treatment option for glioma patients." (PMID 34827600, 2021). "Moreover, the lncRNA, KCNQ1OT1, was reported to confer chemoresistance in gliomas via sponging miR-761 and subsequently upregulating peripheral interface module 1 (PIM1)." (PMID 34268119, 2021). "In addition, KCNQ1OT1 promoted the aggressiveness of glioma cells through the miR-370/CCNE2 (cyclin E2) signaling pathway." (PMID 34827600, 2021). "Similarly, KCNQ1OT1 upregulation and mutation are associated with progression of hepatocellular carcinoma (HCC) and glioma." (PMID 31915311, 2020). "The activation of KCNQ1OT1/miR-370/CCNE2 axis resulted in glioma carcinogenesis." (PMID 29970910, 2018). "KCNQ1OT1 promotes cell malignancy in the KCNQ1OT1-miR-370-CCNE2 axis pathway in glioma." (PMID 29552296, 2018). "Targeting KCNQ1OT1 may represent a promising strategy in glioma therapeutics." (PMID 35935338, 2022). "KCNQ1OT1 C by retrieving PIM1 FrommiR-761 could confer gliomas resistance to TMZ." (PMID 34178658, 2021). "Furthermore, KCNQ1OT1 directly sponges miR-370 in glioma cells." (PMID 31915311, 2020). "The KCNQ1OT1 has been shown to be carcinogenic in several tumors including melanoma, hepatocellular carcinoma (HCC), glioma, and so forth by previous reports." (PMID 35193115, 2022).
hepatocellular carcinoma (16 papers, 2019 to 2025). A malignant tumor that arises from hepatocytes. "Early studies have shown that KCNQ1OT1 is up-regulated and involved in the tumorigenesis of breast cancer and hepatocellular carcinoma." (PMID 31391008, 2019). "KCNQ1OT1 has been shown to mediate the growth of hepatocellular carcinoma by functioning as a ceRNA of miR-504 and also to regulate proliferation and cisplatin resistance in tongue cancer via miR-211-5p-mediated Ezrin/Fak/Src signaling." (PMID 31164794, 2019). "Downregulated miR-29a-3p might account for the tumor promotion of the lncRNA KCNQ1OT1 in hepatocellular carcinoma." (PMID 36338027, 2022). "KCNQ1OT1 is upregulated in OXA-resistant hepatocellular carcinoma (HCC) patient tissues, compared with OXA-sensitive tissues." (PMID 34827600, 2021). "Also, miR-7 expression could be repressed by lncRNA KCNQ1OT1 in oxaliplatin-resistant hepatocellular cancer cells, which accelerated cell resistance to oxaliplatin." (PMID 32714093, 2020). "A previous study suggested that KCNQ1OT1 facilitated tumor growth by competitively sponging miR‐504 and up-regulating cyclin‐dependent kinase 16 (CDK16) in hepatocellular carcinoma." (PMID 32377169, 2020). "In addition, KCNQ1OT1 can competitively target miR-148a-3p and consequently promote the expression of the miR-148a-3p target IGF1R gene in hepatocellular carcinoma cells." (PMID 35498136, 2022). "Conclusively, KCNQ1OT1 similarly exerted positive effect in the treatment of oxaliplatin resistance in liver cancer via miR-7-5p/ ABCC1 axis, offering a unique strategy for the hepatocellular cancer therapy." (PMID 35193115, 2022).